SHANK2 (SH3 and multiple ankyrin repeat domains 2)
Diseases named in the same sentence as SHANK2 in open-access papers (continued):
Sharing a sentence is not in itself a finding about the gene and the disease.
Zinc deficiency (7 papers, 2020 to 2025). A deficiency of the essential metal Zinc; an essential cofactor for many enzymes. "Shank2 proteins have been shown to be zinc-sensitive: For example, Shank2 increases in hippocampal neurons supplemented with zinc, while chronic zinc deficiency induces loss of Shank2/3 and increased incidence of ASD-behaviours." (PMID 34167580, 2021). "At synapses in the CNS, for example, we have previously shown that SHANK2 and SHANK3 are regulated by zinc at developing synapses and lost from synapses in offspring of mice born from mothers with zinc deficiency." (PMID 35682762, 2022). "In line with this, we have previously observed a decrease of synaptic SHANK2 and SHANK3 by direct induction of zinc deficiency both in vitro and in vivo." (PMID 34741005, 2021). "The loss of the zinc-sensitive SHANK proteins SHANK2 and SHANK3, notwithstanding whether caused directly by zinc deficiency or indirectly, may affect synapse function with possibly lasting effects on brain function later in life." (PMID 34741005, 2021). "Furthermore, it has been suggested that zinc signaling through Shank2 and Shank3 controls the AMPA receptor subunit switch in developing neurons, and that zinc deficiency may impair synaptic maturation and circuit formation that underlie ASD etiology." (PMID 33374671, 2020).
depression (6 papers, 2018 to 2025). "Alterations at HACE1 and SHANK2 loci imply potential mechanisms, such as oxidative stress in the brain, underlying depression." (PMID 32616021, 2020). "However, in controls, only SHANK2 rs55678639 was associated with depression." (PMID 37303955, 2023). "Genes associated with depression or neuro-diseases were found in this study, such as ABCG1, ASMTL, CACNA1F, COX7A1, GRID2, HTR3E, and SHANK2." (PMID 37766304, 2023). "Our results are strengthened by our comprehensive bioinformatics analysis that is integrating multiple lines of evidence point at a role for HACE1 and SHANK2 in the pathophyology of depression." (PMID 32616021, 2020). "In nonmigraine subjects, only SHANK2 rs55678639 was associated with depression." (PMID 37303955, 2023).
Alzheimer disease (5 papers, 2016 to 2023). A progressive, neurodegenerative disease characterized by loss of function and death of nerve cells in several areas of the brain leading to loss of cognitive function such as memory and language.
breast carcinoma (4 papers, 2017 to 2021). "KIF3C is found to be highly expressed in breast cancer, KIF3C and SHANK2 are both related to axons transmitting neural signals, and poor prognosis of tumor, but its role in melanoma remains to be further studied." (PMID 32547879, 2020). "The involvement of FAK in promoting breast cancer metastasis was also shown upon its interaction with Gpx1 or the protein arginine methyltransferase 7 (PRMT7)-dependent methylation of the scaffolding protein SH3 and multiple ankyrin repeat domains 2 (SHANK2)." (PMID 33562737, 2021).
glioma (3 papers, 2021 to 2024). A benign or malignant brain and spinal cord tumor that arises from glial cells (astrocytes, oligodendrocytes, ependymal cells). "Through comprehensive analysis, we found a significant association between higher SHANK2 expression and improved survival outcomes across various glioma subtypes." (PMID 39397895, 2024). "In glioma tissues, SHANK2 is markedly elevated compared to normal brain tissue, particularly in patients aged 60 and younger." (PMID 39397895, 2024). "The mechanistic implications of SHANK2 in glioma are intriguing, considering its primary role in synaptic assembly and cognitive function." (PMID 39397895, 2024). "As we delve into the potential role of the SHANK2 gene in glioma prognosis, it is imperative to understand the foundation upon which this research stands." (PMID 39397895, 2024). "The study also introduces a multivariate prognostic model incorporating SHANK2, providing a novel perspective on glioma prognosis." (PMID 39397895, 2024). "This dichotomy highlights SHANK2's expression as a differentially impactful factor in the complex landscape of glioma prognosis." (PMID 39397895, 2024). "To further validate the clinical relevance of SHANK2, we conducted cellular experiments involving siRNA-mediated knockdown of SHANK2 in U87 and A172 glioma cell lines." (PMID 39397895, 2024). "In conclusion, while our study presents a compelling case for SHANK2 as a prognostic marker in glioma, it is imperative to approach these findings with a view toward comprehensive validation and investigation." (PMID 39397895, 2024). "Quantitative real-time PCR (qPCR) and Western blot analyses confirmed the successful knockdown of SHANK2, and subsequent MTT assays revealed that silencing SHANK2 significantly promoted glioma cell proliferation." (PMID 39397895, 2024). "For a more comprehensive visualization, we conducted the Kruskal–Wallis test regarding the SHANK2 expression in glioma, revealing distinct patterns across various clinical categories." (PMID 39397895, 2024). "The potential for SHANK2 to influence glioma prognosis is clear, but the path from genetic marker to therapeutic target is a complex one that requires careful navigation through both clinical and molecular research landscapes." (PMID 39397895, 2024). "In the study, we explored the correlations between SHANK2 expression levels and various patient characteristics in a cohort of 699 glioma cases." (PMID 39397895, 2024). "While the involvement of SHANK2 in various cancers is beginning to be elucidated, its role in glioma, particularly in influencing prognosis, remains largely unexplored." (PMID 39397895, 2024). "These patterns underscore the potential role of SHANK2 expression as a differential marker in glioma biology and patient stratification." (PMID 39397895, 2024). "Knockdown of SHANK2 in U87 and A172 glioma cell lines was confirmed by both RT-qPCR and Western blot analysis." (PMID 39397895, 2024). "It is possible that SHANK2's influence extends beyond the synapse, affecting glioma cell biology through alterations in intracellular signaling cascades, cellular adhesion, and migration patterns." (PMID 39397895, 2024). "No published evidence was available as to the roles of the remaining eight underexpressed gene signatures (CHST9, CSDC2, ENHO, FERMT1, IGFN1, LINC00836, MGAT4C and SHANK2) regarding glioma pathogenesis or prognosis." (PMID 35456975, 2022). "This study investigates the prognostic significance of SH3 and multiple ankyrin repeat domains 2 (SHANK2) gene expression in glioma patients, using data from The Cancer Genome Atlas (TCGA), the Genotype-Tissue Expression (GTEx) project, and the Gene Expression Omnibus (GEO)." (PMID 39397895, 2024). "These potential pathways may impact glioma cell proliferation and invasiveness, suggesting that SHANK2's role in the brain could be dual-faceted, encompassing both neuronal function and tumor suppression." (PMID 39397895, 2024).
glioma (continued). "While the retrospective nature of the study presents limitations, our results suggest that SHANK2 expression could serve as a valuable biomarker for glioma prognosis and inform future therapeutic strategies." (PMID 39397895, 2024). "Moreover, gliomas with mutated IDH status and those with 1p/19q codeletion are associated with higher SHANK2 expression, suggesting a potential link between SHANK2 and these genetic alterations." (PMID 39397895, 2024). "Furthermore, our findings pose questions about SHANK2's interaction with current therapeutic strategies for glioma." (PMID 39397895, 2024). "Finally, we constructed a nomogram, a predictive tool that amalgamates various prognostic factors, such as gender, age, and histological features, along with SHANK2 expression levels, to estimate the survival probabilities for glioma patients." (PMID 39397895, 2024). "Our findings significantly enhance our understanding of the SHANK2 gene's role in glioma." (PMID 39397895, 2024). "Similarly, the survival outcomes for glioma patients, as stratified by SHANK2 expression and glioma characteristics, exhibit intriguing patterns." (PMID 39397895, 2024). "Notably, SHANK2's higher expression levels correlating with increased survival rates introduce the possibility of a novel protective genetic factor within the glioma context, distinguishing it from more established prognostic markers." (PMID 39397895, 2024). "Moreover, the molecular mechanisms of SHANK2 in glioma remain unknown." (PMID 39397895, 2024). "A gradation in SHANK2 levels is observed across different WHO grades, with a notable peak at Grade 2 and a subsequent decline in Grades 3–4 gliomas." (PMID 39397895, 2024). "The absence of comprehensive studies examining SHANK2 in glioma contexts suggests a crucial area for future research." (PMID 39397895, 2024). "The high frequency of junctions in the relatively large, yet not heavily up-regulated SHANK2 (785 kb) and TENM4 (788 kb) suggests that they are “collateral damage” of the amplifications, a hypothesis that has been described in glioma." (PMID 34891161, 2021).
Angelman syndrome (2 papers, 2012 to 2022). A neurogenetic disorder characterized by severe intellectual deficit and distinct facial dysmorphic features. "Remarkably, all three patients with SHANK2 de novo deletions also carried rare inherited genetic imbalances at chromosome 15q11–q13, a region associated with Angelman syndrome, Prader-Willi syndrome and other neuropsychiatric disorders, including ASD." (PMID 22346768, 2012).
esophageal cancer (2 papers, 2019 to 2021). A primary or metastatic malignant neoplasm involving the esophagus. "For example, in a recent analysis of esophageal cancer, a tumor type with frequent 11q13 amplification, SHANK2 overexpression was identified as one of the most significant factors for poor patient survival, second only to tumor stage." (PMID 32661924, 2021). "Analysis of uterine corpus endometrial carcinoma and esophageal carcinoma, two cancer types with the most prominent SHANK2 overexpression, showed that expression of SHANK2 positively correlates with CTGF and CYR61." (PMID 32661924, 2021). "Among our methylation signatures, some genes have been reported in the onset and progression of BE and esophageal cancer or the prognosis of esophageal cancer, such as TRIM15, TACC3, SHANK2, and MCC." (PMID 31834866, 2019).
esophageal squamous cell carcinoma (2 papers, 2015 to 2021). Esophageal squamous cell carcinoma (ESCC) is a type of esophageal carcinoma (EC) that can affect any part of the esophagus, but is usually located in the upper or middle third. "SHANK2 has been suggested as a novel oncogene as its over-expression in esophageal squamous cell carcinoma is associated with cell proliferation and protection against cell death." (PMID 26039411, 2015). "A recent study of esophageal squamous cell carcinoma from South Africa also confirmed SHANK2 overexpression via immunohistochemistry staining." (PMID 32661924, 2021).
Obesity (2 papers, 2021 to 2025). Accumulation of substantial excess body fat. "A double knockout of Shank1 and Shank2 in mice has shown a significant reduction in the activation levels of the Akt signaling pathway, which is one of the primary signaling pathways involved in the pathogenesis of T2D and associated obesity." (PMID 41465472, 2025).
oral squamous cell carcinoma (2 papers, 2008 to 2020). "Indeed, recurrent coamplification of the cytoskeleton-associated genes CCTN and SHANK2 with the cell-cycle control gene CCND1 has been observed in oral squamous cell carcinoma." (PMID 18268492, 2008). "Co-amplification of CTTN, SHANK2 and CCND1 genes has been reported previously in oral squamous cell carcinoma." (PMID 32252688, 2020). "The SHANK2 and CTTN genes are in close proximity (30 kb) and are often co-amplified in oral squamous cell carcinoma." (PMID 32252688, 2020).
brain tumors (1 paper, 2022). "SHANK2 plays an evolutionarily conserved role in the regulation of Hippo signaling, which promotes tumorigenesis and metastasis of several cancers including GBM, although scant data exist on the role of Hippo signaling in brain tumors." (PMID 35456975, 2022).
glioblastoma (1 paper, 2024). The most malignant astrocytic tumor (WHO grade IV). "Histological type and WHO grade also demonstrated significant associations with SHANK2 levels; notably, glioblastoma cases predominantly exhibited low SHANK2 expression, whereas oligodendrogliomas showed high expression levels." (PMID 39397895, 2024). "Interestingly, LGGs exhibit higher SHANK2 expression than glioblastomas." (PMID 39397895, 2024). "Age above 60, histological type (notably glioblastoma), and genetic markers (IDH status and 1p/19q codeletion) were highlighted as significant prognostic factors, alongside SHANK2 expression levels." (PMID 39397895, 2024). "In stark contrast, SHANK2's expression level does not significantly influence survival in patients with glioblastomas or those with wild-type IDH status and 1p/19q codeletion." (PMID 39397895, 2024).
infantile epilepsy (1 paper, 2025). "At the protein level, western blots validated expression changes in CBS (mental retardation), NEAS/SPTAN1 (associated with infantile epilepsy), FBLN1 (cardiac morphogenesis), FXR1 (muscle development), and SHANK2 (neuronal differentiation in the retina)." (PMID 39508990, 2025).
kidney cancer (1 paper, 2022). Primary or metastatic malignant neoplasm involving the kidney. "A pooled analysis of 1509 kidney cancer tissues and 414 adjacent normal tissues from 19 independent studies demonstrated that SHANK2 was downregulated in kidney cancers (p < 0.001)." (PMID 36231770, 2022). "A pooled analysis of public gene expression datasets showed downregulation of SHANK2 in kidney cancer specimens, suggesting that this gene might play an important role during kidney carcinogenesis." (PMID 36231770, 2022). "To further evaluate the potential functions of SHANK2 in RCC, we used publicly available kidney cancer datasets." (PMID 36231770, 2022).
liver cancer (1 paper, 2021). An epithelial or non-epithelial malignant neoplasm that arises from the liver. "Deletion of PDZ from SHANK2 also diminished its ability to deregulate the phosphorylation, localization and activity of YAP and to promote liver cancer formation in vivo." (PMID 32661924, 2021).
oropharyngeal cancer (1 paper, 2021). Carcinoma, predominantly squamous cell, arising from the epithelial cells of the oropharynx. "Several studies noted SHANK2’s amplification in esophageal and oropharyngeal cancer and its association with poor prognosis." (PMID 32661924, 2021).
Polydipsia (1 paper, 2023). Excessive thirst manifested by excessive fluid intake. "The effects of other genes such as the neurexin family gene, CNTNAP2, and SHANK2 gene on polydipsia remained to be clarified." (PMID 37484674, 2023).
Sepsis (1 paper, 2023). Sepsis is defined as life-threatening organ dysfunction caused by a dysregulated host response to infection. "We found that homozygous and heterozygous Shank3 deficiency, but not Shank2 and Trpv1 deficiency, aggravates hypothermia, systemic inflammation (serum IL-6 levels), and sepsis mortality in mice, induced by lipopolysaccharide (LPS)." (PMID 36845137, 2023).
X-linked intellectual disability (1 paper, 2021). An X-linked intellectual deficiency in which not enough information is known, reported or published to indicate whether a gene causes non-syndromic or syndromic presentations. "Dlg3 is implicated in X-linked intellectual disability, while Shank2 is a known risk gene for ASD; therefore, dysregulation of these genes may contribute to neurological and behavioral abnormalities." (PMID 34259631, 2021).
neurodevelopmental disorder (22 papers, 2016 to 2025). A behavioral and cognitive disorder with onset during the developmental period that involves impaired or aberrant development of intellectual, motor, or social functions. "Further information about the functional impact of SHANK2 mutations in humans is needed for a better understanding of the molecular pathology of neurodevelopmental disorders." (PMID 33483523, 2021). "Shank2 Δex7−/− mice reproduce several phenotypes associated with ASDs, a neurodevelopmental disorder." (PMID 30023428, 2018). "Previous studies have identified eighteen patients with neurodevelopmental disorder harboring de novo variants in the human SHANK2 gene, and we identified three additional patients with de novo variants of SHANK2 in our clinical screening cohort." (PMID 36768529, 2023). "There are three main classes of SHANK proteins: namely, SHANK1, SHANK2, and SHANK3, and mutations in these proteins correlate with neurodevelopmental disorders." (PMID 33483467, 2021). "So far, mounting evidence has established a link between SHANK2 and neurodevelopmental disorders by overexpressing SHANK2 mutants in primary culture neurons, utilizing iPSCs carrying patient-derived SHANK2 mutants or employing gene-edited SHANK2 knockdown models." (PMID 38704506, 2024). "Notably, the mRNA levels of ASD‐related risk genes like NLGN1, SHANK2, SHANK3, and CNTNAP2 are influenced by the prenatal suppression of histone deacetylase family, which are linked to neurodevelopmental disorders." (PMID 37807632, 2023). "Given that ASD is a neurodevelopmental disorder and people with ASD may show signs of behavioral inflexibility in childhood, we tested whether juvenile Shank2-KO mice also show deficits in reversal learning." (PMID 36192805, 2022).